CD4 (CD4 molecule)
Diseases named in the same sentence as CD4 in open-access papers (continued):
Sharing a sentence is not in itself a finding about the gene and the disease.
infection (continued). "The recruitment of neutrophils or CD4+ T cells (data not shown) was similar between both groups at the different times of infection." (PMID 23802100, 2013). "Here we demonstrate that latency can be efficiently established via direct infection of non-proliferating CD4+ T cells in the presence of DC." (PMID 24339779, 2013). "Whilst the role of IL-27 in controlling T cell apoptosis has not been directly examined, IL-6 and IL-12 are both known to exert anti-apoptotic effects on CD4+ T cells and concentrations of both these cytokines are significantly increased in WSX-1−/− mice during infection." (PMID 24244314, 2013). "We find that CD4+ T lymphocytes, recruited in dependence upon their expression of the chemokine receptor CXCR3, mediate activation of intestinal mucosa inflammatory monocytes via secretion of IFN-γ, in turn resulting in control of infection." (PMID 24130498, 2013). "In macaques treated with DV056 blood CD4 T cell counts were transiently increased at day 4 and day 21 post infection, although the pattern of changes in CD4+ T cell counts over time was not significantly different between groups." (PMID 23935491, 2013). "To study the cellular immune responses generated during Brucella infection we examined CD4+ and CD8+ T cell activation at several time points post-infection by measuring the surface expression of CD25, CD44 and the intracellular synthesis of effector molecules such as Granzyme B and IFN-γ." (PMID 24367519, 2013). "Even though IFN-DCs expressed CD4 and CCR5, these cells were refractory to productive infection." (PMID 23593001, 2013). "Moreover, the upregulation of the activated markers CD69, CD44, CD40L, and the downregulation of CD62L were observed in the CD4+ and CD8+ T cells following infection." (PMID 23555767, 2013). "Furthermore, high percentages of DCs and macrophages, but also B cells, CD4+ and CD8+ T cells produce IL-10 nine and thirty days after Clone 13 infection when assessed in IL-10 reporter (VertX) mice." (PMID 24244162, 2013). "Both the TB10.4 and ESAT-6 specific immune response in control animals (infection-driven) consisted for comparison primarily of IFN-γ+TNF-α+ CD4 T at both time-points (data not shown)." (PMID 24349004, 2013). "Such TN cell infection, although a tenth as frequent as in memory cells, contrasts with their low CCR5 expression and with the usual dogma of a preferential CXCR4-restricted infection thought to affect naive CD4 T cells during acute infection." (PMID 23691172, 2013). "In contrast, in WSX-1−/− mice the frequencies, and correspondingly the total numbers, of effector CD4+ T-bet+ T cells expressing KLRG-1 rapidly increased between day 9 and day 11 of infection, such that more than 50% of all splenic effector CD4+ T-bet+ cells expressed KLRG-1 on day 14 of infection." (PMID 23593003, 2013). "At variance with the infection of activated primary cells it is possible to infect directly resting (not activated) CD4+ T cells." (PMID 23803414, 2013). "This could be due to redirecting of CD4 biasing virus entry into DC through DC-SIGN and subsequent efficient trans infection of T cells." (PMID 24278768, 2013). "Here, we characterized the molecular interactions at the infectious synapse between mDC harboring HIV-1 and non-activated primary CD4+ T cells where trans-infection takes place." (PMID 23590845, 2013). "Our study provides much earlier information about the spread of HIV than a previous study performed in late PHI (i.e., 6 months after infection), and that did not distinguish between resting and activated CD4 T-cell subsets for HIV-DNA quantification." (PMID 23691172, 2013). "The first involved the infection of non-polar CD4+ T cells, which are considered to be the in vitro counterparts of latently infected central memory T cells in vivo." (PMID 24156270, 2013).
infection (continued). "Persistent LCMV clone 13 infection is ultimately cleared in B6 mice by day 60, and epitope-specific CD8 T cells return, except for the high affinity NP396 T cells, which are eliminated by apoptosis in the presence of functional LCMV-specific CD4 T cells." (PMID 24391647, 2013). "We next compared splenic CD4+ and CD8+ T cell responses following WNV H8912 or NY99 infection." (PMID 23785537, 2013). "The number of CD4+ T cells declined to ~200 cells/μl at 3 weeks after inoculation, and remained at zero level throughout the infection in MM376 and MM340, whereas in MM273, the number of CD4+ T cells recovered to ~300 cells/μl from 12 to 20 wpi, but after 46 wpi, it maintained a zero level." (PMID 23885255, 2013). "Hence, we determined the relative proportions of CD4+ and DN iNKT cells in the lung of IAV infected BALB/c, PD-L1−/− and PD-L2−/− at various days post infection." (PMID 23555047, 2013). "The levels of human CD4+ T cells in the infected mice did not change throughout the course of infection." (PMID 23527295, 2013). "Moreover, the sustained presence of activated CD4+ and CD8+ T cells throughout the course of infection is driven by the bacillary load in the lungs." (PMID 23448601, 2013). "Interestingly, mice selectively depleted for only CD4+ T cells or CD8+ T cells are able to resolve and survive infection." (PMID 23349802, 2013). "PD-1+ CD4 T cells represented essentially central memory T cells, while PD-1+ CD8 T cells were a mix of central and effector memory T cells with only minor variations over time post infection." (PMID 23555918, 2013). "Since HTLV-I has a high tendency to infect CD4+CD25+high T regulatory cells, there is a possibility that the changes in the function of these cells are due to this infection and this justifies the prevalence of recurrent aphthous stomatitis in HTLV-I positive individuals." (PMID 24470876, 2013). "Since the naïve mice failed to control the PyNL infections, the impact of the CD4 depletion on BCG-induced protection is difficult to interpret." (PMID 23861742, 2013). "Others argue that it takes such a short time to progress from time of infection to CD4 counts below 500 and 350 cells/μl that it is not worth the bother to delay initiation of ART as the person will be in need shortly anyway." (PMID 23767777, 2013). "At late phase of infection, high expression of both CCL19 and CXCL12 was observed only in control mice and correlated with the maintenance and the lymphoid organization of immune infiltrates composed of CD4+ and CD8+ T cells, macrophages, DC and FDC." (PMID 23717393, 2013). "Analysis on day 5 post infection revealed that CD8+ T cell depleted mice expressed similar overall levels of IL-10 mRNA as undepleted controls, while CD4+ T cell depleted, clodronate liposome treated mice and DC specific IL-10 knockout mice (Il-10fl/flxCD11c-Cre+ mice) exhibited reduced levels." (PMID 24244162, 2013). "Thus, in contrast to the MLN, ICOS deficiency resulted in an elevated production of Type 2 cytokines by CD4+ T cells within the LP, suggesting that ICOS downregulates Th2 cells at the infection site." (PMID 23319295, 2013). "Of the 14 Th1 response genes tested, the expression levels of 8 genes (IL2, IFNG, CSF2, TLR4, CD4, IRF1, SOCS5 and STAT4) were significantly elevated at 2 weeks and several of these (IL2, IFNG, TLR4, CD4 and STAT4) had similar expression levels at 4 and 8 weeks post-infection." (PMID 23448601, 2013). "The number of Tregs increases in response to infection by pathogenic microorganisms, including the hepatitis B virus; this increase inhibits CD4+ and CD8+ T-cell activation, proliferation and cytokine secretion, thus affecting the host immune response to infection and leading to chronic infection." (PMID 23759077, 2013). "In this last publication, however, the critical role of CD4+ Th1 cells in CD8+ T cell mobilization to the site of infection for host survival was not established." (PMID 24068938, 2013).
infection (continued). "However, infection of B6.CCR7-/- mice with the parasite Toxoplasma gondii, which requires a CD4+ Th1 response, results in death during the acute phase of the disease due to uncontrolled parasite replication and dissemination." (PMID 24205367, 2013). "Flow cytometric analysis of Foxp3+CD4+ cells at 6 and 10 weeks post-infection indicated that the transfer of WT Tregs did not increase the frequency of this population in the lungs of TLR2KO mice, which were significantly lower than WT controls at 6 weeks." (PMID 23785280, 2013). "Given that the infection of DCs with the Vpx-containing HIV-1 triggers activation of DCs and cocultured CD4+ T-cells, these studies imply that the chimeric HIV-1 might be used to design DC-based vaccines to induce an enhanced innate immune response." (PMID 24523981, 2013). "An increase was observed in the frequency of pSTAT5+ CD4 T cells that responded to ex vivo IL-2 stimulation regardless of infection, indicating that neutrophils suppress CD4 T cell responsiveness to IL-2." (PMID 23754944, 2013). "Nonetheless, these data together with post-challenge recall responses revealed that the paucity of anti-rApa T cell responses after primary infection, especially CD4+ T cell responses, is not due to an intrinsic inability of rApa to induce these responses." (PMID 24130497, 2013). "In our experiments, we observed a similar lack of in vitro proliferative capacity in liver CD4+ T cells that were isolated on day 7 of infection." (PMID 24312297, 2013). "Addition of AZT, prevents de novo infection of CD4+ T-cells indicating that intracellular p24 detected is not residual inocula." (PMID 23614015, 2013). "In line with the known immunomodulatory effects of H. pylori, the expression of CD-markers related to T helper (CD4/GATA4) and regulatory T cells (CD25/FOXP3) was suppressed upon an 11-month infection with H. pylori SS1, and this phenomenon was most pronounced in Cav1-KO mice." (PMID 23592983, 2013). "Though CD4+T cell numbers were not increased in vivo upon challenge infection of vaccinated mice, IFN-γ producing CD4+T cells likely assisted the phagocytes in parasite killing, and served as helper cells for the development of CD8+ CTL effector cells." (PMID 23555672, 2013). "We noted CD4+ and CD8+ T cells of WNV H8912 or NY99-infected mice produced similar levels of IFN-γ upon ex vivo stimulation with WNV peptides on days 8 and 38 post-infection." (PMID 23785537, 2013). "Cells, such as CD4+ and CD8+ T lymphocytes and dendritic cells may explain the overall percentage increase in inflammatory infiltrates observed at day 10 post infection in mock-treated infected mice." (PMID 23951095, 2013). "Regarding new vaccines against infection with M.tb, recombinant MVA expressing Ag85A (MVA85A) has been shown to boost and improve protection of BCG in mice, cattle and rhesus monkeys and to induce both CD4 and CD8 T cells." (PMID 23977248, 2013). "One of the mechanisms by which DCs can mediate virus spread is via the trans infection pathway whereby DCs capture HIV-1 particles and retain them in an infectious state without getting infected, and pass these infectious particles to CD4+ T cells upon initiation of cellular contacts." (PMID 23593001, 2013). "There was, however, a negative correlation (ρ = -0.36, p = 0.34) between time post infection and recipient to transmitter replication ratio in α4β7 high CD4+ T cells, although it was not statistically significant." (PMID 24369910, 2013). "Numerous reports indicated exacerbation of chronic LCMV infections in the absence of CD4 T cells, preventing eventual control of infection." (PMID 23717308, 2013). "It is therefore likely that developing infection-resistant, HIV-specific CD4+ T-cells may greatly reduce viral pathogenesis possibly leading to the development of a natural controller phenotype." (PMID 24287598, 2013). "Thus, feeding of apoptotic, uninfected, activated CD4+ T cells to DC can inhibit both HIV-1 cis and trans infection." (PMID 24278768, 2013).
infection (continued). "In contrast, pre-incubation of CD4+ T-cells with E2 did not reduce infection levels with HIV-1IIIB, measured as released p24 or intracellular p24 (bottom row)." (PMID 23614015, 2013). "Our adoptive transfer study supports this since purified CD4+ T cells were able to mediate partial protection to a MNV-3 primary infection even when recipient mice lacked other adaptive immune cells (i.e. RAG1−/− recipients)." (PMID 24039576, 2013). "Indeed, macaque studies have shown that helminthic parasitic infections can exacerbate infection with SIV due to alterations in the cytokine milieu and increased frequency of Th2 CD4+ T-cells." (PMID 23824043, 2013). "However, our flow cytometry data indicate systemic and mucosal production of IL-17 by CD4+ T cells, suggesting for the first time a role for Th17 responses in the clearance of EAEC infections." (PMID 23469071, 2013). "Two out of 8 mice did not survive challenge infection after combined removal of CD4- and CD8-positive T-cells." (PMID 24376753, 2013). "While numerous anti-glycan antibody changes were observed in this phase of infection, none showed a statistically significant correlation with outcomes (viral load and CD4+ levels)." (PMID 24086502, 2013). "Even though infected myeloid cells in vivo do not dramatically change MHC class II cell surface expression levels within the first weeks of infection, virulent mycobacteria may still inhibit activation of MHC class II-restricted CD4+ T cells." (PMID 23861965, 2013). "In fact, T cell-to-T cell infection involves many factors that are part of APC-to-T cell trans infection, including expression of CD4 on T cells and formation of a virologic synapse and evasion of neutralizing antibody and the viral inhibitory effects of antiretroviral treatment (ART)." (PMID 24278768, 2013). "It has long been considered that early tularemic infection is controlled by T cell-independent events, as T cell depleted mice (depleted of both CD4+ and CD8+ T cells) survive initial infection, but fail to clear bacteria and succumb to infection several weeks after inoculation." (PMID 23349802, 2013). "Tregs that were isolated from liver during the acute phase of infection suppressed naïve CD4+ T cell proliferation, but did not suppressed the proliferation of liver effector CD4+ T cells (Teffs) from the acute phase." (PMID 24312297, 2013). "In contrast to Itgb8 (CD11c-Cre) mice, Itgb8 (CD4-Cre) mice showed no protection from infection with T.muris and showed an identical parasite-specific IgG2a/IgG1antibody bias which is associated with development of a chronic infection." (PMID 24098124, 2013). "However, tetherin expression was shown to be increased in mononuclear leukocytes, including CD4+ T lymphocytes, from untreated HIV-positive patients when compared to cells of uninfected controls during the acute phase of infection." (PMID 24167505, 2013). "Development of virus-specific CD4 T cells producing IL-10 has been reported for numerous herpes virus infections, such as VZV, HSV, CMV, and EBV infections." (PMID 23717308, 2013). "We examined the percentage of CD4+ T cells or CD4+ Tcm cells in CD3+ T lymphocytes from peripheral blood (PBL), lymph node (LN) and gut (GUT) prior to SHIV-1157ipd3N4 inoculation (on day 540 after primary infection) in the SIR and SIS groups." (PMID 24023734, 2013). "Importantly, proliferation of both the CD4+ and CD8+ spleen T cells dropped to about 10% at later time points (20 and 24 weeks post-infection)." (PMID 23448601, 2013). "Interestingly IL-17-producing CD4+ and CD8+ cells were present in the gut and peripheral circulation despite their reported paucity following infection with virulent SIVmac reflecting the attenuated nature of the viruses used in this study." (PMID 23738926, 2013).
infection (continued). "To determine whether mDC or pDC were facilitating latency in resting CD4+ T cells, we next co-cultured sorted mDC and pDC with SNARF-labelled resting CD4+ T cells for 24 hours prior to infection, and experiments were performed." (PMID 24339779, 2013). "Remarkably, unlike wild-type HIVLAI which rapidly depletes peripheral blood CD4+ T cells, infection with HIVLAIΔvif did not deplete CD4+ T cells in the periphery despite sustained viral replication." (PMID 23555255, 2013). "During the acute phase of infection, virus-specific CD8 T cells are important for controlling viral replication, but NK and CD4 T cells are not significantly contributing to keep the infection in check." (PMID 23738889, 2013). "Finally, to assess the effect of Prostratin and Gö6850 on viral entry directly, IL-2-supplemented MYA-1 CD4+ T-cells were pre-incubated with Prostratin, Prostratin plus Gö6850, Gö6850 or DMSO for 24 h prior to infection with FIV." (PMID 23201205, 2013). "Two basic principles of HIV-1 trans infection were established with this pioneering study, that is, that antigen-specific activation of the T cells results in greater trans infection by the MDM and that anti-CD4 and anti-gp120 antibodies block trans infection." (PMID 24278768, 2013). "At day 5 post-infection, non-proliferating (SNARFhi) CD4+ T cells that were not productively infected (EGFP−) were sorted (purity was always >99%)." (PMID 24339779, 2013). "ANDV infection resulted in a higher expression of CD4 and TCR-β RNAs, and comparable expression of CD8α, suggesting that a robust CD4+ T cell response may contribute to viral clearance." (PMID 23383148, 2013). "CD4 + CD25+ and CD4 + CD25- T cells appear to possess different activation requirements, modulated by viral titer and cytokine stimuli, to reach threshold activation levels required to harbor a productive FIV infection." (PMID 23829177, 2013). "In our study we observed suppression of HIV-infection in CD4+ T-cells when they were pre-treated with E2 prior but not after infection." (PMID 23614015, 2013). "CD4+ and CD8+ T cell responses persisted in the spleen up to 15 days post-infection." (PMID 24367519, 2013). "To define the kinetics of altered intrahepatic accumulation of CD4+ T cells in WSX-1−/− mice during malaria infection, we compared the frequencies and total numbers of intrahepatic CD4+ T cells in WT and WSX-1−/− mice on various days of infection." (PMID 24244314, 2013). "CD4+ T cells do not commit to the Tfh lineage until days 6–10 of infection 39, and at day 7 of H. polygyrus infection, on the cusp of Tfh-cell commitment, the numbers of IL-4 and IL-13 producing CD4+ T cells in the MLNs were equivalent in WT and ICOS−/− mice." (PMID 23319295, 2013). "However, on day 21 after infection, the percentage of IFN-γ-producing CD4+ T cells decreased inside the liver and we found a considerable percentage of CD4+ T cells producing IL-10, including double IFN-γ/IL-10 producers, and some IL-10-producing DCs." (PMID 24312297, 2013). "After infection, cells were analyzed for the expression of costimulatory molecules (CD86, CD80, and PD-L1), cytokine production, and the ability to stimulate allogenic CD4+ T cell proliferation." (PMID 23829893, 2013). "On the other hand, infection with 2W1S-expressing L. monocytogenes induced no IFNγ expression among 2W1S-specific CD4 T cells in postpartum females that had delivered 2W1S+ pups." (PMID 24391885, 2013). "► Prostratin reactivates productive infection from FIV infected, IL-2-depleted feline CD4+ T-cells." (PMID 23201205, 2013). "We next determined if both human and murine CD169 could transfer captured HIV-1 particles to CD4+ T cells and MLV particles to murine cells, a mechanism of retroviral trans infection." (PMID 23593001, 2013).